PPP4R3B (protein phosphatase 4 regulatory subunit 3B)
Description:
Regulatory subunit of serine/threonine-protein phosphatase 4 (PP4). May regulate the activity of PPP4C at centrosomal microtubule organizing centers.
Synonyms: KIAA1387; PP4R3B; SMEK2; PSY2; FLFL2; FLJ31474; smk1
Tractability: PROTAC: ubiquitination databases record sites on it.
Target class: Protein phosphatase regulatory subunit; Phosphatase; Enzyme; Protein Phosphatase
Gene: Protein-coding gene on chromosome 2 (55,547,292 to 55,618,880, reverse strand). Ensembl gene ENSG00000275052.
Subcellular location: Cytoplasm; Cytoplasm, cytoskeleton, microtubule organizing center, centrosome; Nucleus
Subcellular location (Human Protein Atlas): Nuclear speckles; Nucleoplasm; Centrosome
Gene Ontology:
Molecular function: protein phosphatase activator activity; protein phosphatase regulator activity
Biological process: regulation of double-strand break repair; DNA damage response
Cellular component: centrosome; chromatin; nuclear speck; nucleoplasm; protein phosphatase 4 complex; cytoplasm; nucleus
Genetic constraint (gnomAD): Loss-of-function variants: 36 observed, 59.22 expected, observed/expected ratio (o/e) 0.61, 90% interval 0.47 to 0.8. The upper end of that interval is the gene's LOEUF score, 0.8, which puts it in group 3 of 6, group 1 being the genes least tolerant of losing a copy. Missense variants: 771 observed, 814.11 expected, observed/expected ratio (o/e) 0.95, 90% interval 0.89 to 1. Synonymous variants: 326 observed, 281.1 expected, observed/expected ratio (o/e) 1.16, 90% interval 1.06 to 1.27.
Homologues: Orthologues: chimpanzee PPP4R3B (99% identical), dog PPP4R3B (95% identical), pig PPP4R3B (94% identical), rabbit PPP4R3B (93% identical), mouse Ppp4r3b (93% identical), macaque PPP4R3B (93% identical), guinea pig PPP4R3B (91% identical), rat Ppp4r3b (90% identical), tropical clawed frog ppp4r3b (90% identical), Drosophila melanogaster flfl (55% identical), Caenorhabditis elegans smk-1 (37% identical), zebrafish ppp4r3b (35% identical). Paralogues in human: PPP4R3A (71% identical), PPP4R3C (60% identical).
Diseases named in the same sentence as PPP4R3B in open-access papers:
PPP4R3B is named in the same sentence as 12 diseases in open-access papers, as found by Europe PMC text mining. Sharing a sentence is not in itself a finding about the gene and the disease. The quoted sentences say what the papers report.
leukemia (1 paper, 2017). A malignant (clonal) hematologic disorder, involving hematopoietic stem cells and characterized by the presence of primitive or atypical myeloid or lymphoid cells in the bone marrow and the blood. "Additionally, qRT-PCR analyses of the other PPP4 regulatory subunits Ppp4r1, Ppp4r3a, and Ppp4r3b were performed to validate specific knockdown of Ppp4r2 in the MLLT3-KMT2A leukemia model." (PMID 29221109, 2017).
PPP4R3B also shares sentences with these, for which no sentence is quoted: cancer (2 papers); Hypercholesterolemia (2); rectal adenocarcinoma (2); tumour (2); bladder cancer (1); COVID-19 (1); epilepsy (1); hyperhomocysteinemia (1); hypersarcosinemia (1); rectal cancer (1); thyroid cancer (1).